TRPV5 (transient receptor potential cation channel subfamily V member 5)
Diseases named in the same sentence as TRPV5 in open-access papers (continued):
Sharing a sentence is not in itself a finding about the gene and the disease.
tumor (6 papers, 2014 to 2025). "The mRNA expression of TRPV2/3 was upregulated while the expression of TRPV5/6 was downregulated in ccRCC tumor tissues." (PMID 35558077, 2022). "The results showed that TRPV2 and TRPV3 were upregulated in ccRCC tumor tissues, whereas TRPV5 and TRPV6 were downregulated in tumor tissues." (PMID 35558077, 2022). "Taken together, these findings confirmed that VDR functions as a tumour suppressor in RCC cells and suppresses the proliferation, migration and invasion of RCC through regulating the expression of TRPV5." (PMID 29659618, 2018). "Generally, mRNA and proteins of TRPV5 and TRPV6 are up-regulated in tumour tissues and cell lines when compared with normal and correlate with tumour progression 8,31,33." (PMID 25164318, 2014).
cancer (4 papers, 2017 to 2022). A tumor composed of atypical neoplastic, often pleomorphic cells that invade other tissues. "TRPV3 and TRPV5 were hypomethylated in most cancer types, while TRPV4 was hypermethylated (P <0.05)." (PMID 35174089, 2022). "Kaplan-Meier survival analysis indicated that the hypermethylation of TRPV1 in LAML and BLCA, TRPV4 in SARC and UCEC, TRPV5 in BLCA, TRPV2 in ACC, and SARC cancers was associated with a poor prognosis in most tumors." (PMID 35174089, 2022). "For example, TRPA1, TRPC1, TRPV4, TRPV5, and TRPV6 exhibited higher CNV amplification, while TRPV1, TRPV2, TRPV3, and TRPC3 exhibited frequent CNV loss in cancer." (PMID 35614079, 2022). "For example, TRPV5 and TRPV6 were down-regulated in most cancers, while TRPV2 and TRPV3 tend to be up-regulated in most cases." (PMID 35174089, 2022). "Subsequently, the CNV percentage analysis in specific cancer subtypes of Hete Amp and Hete Del showed that TRPV1-6 (except for TRPV4) in KIRP, TRPV4 in ACC, TRPV6 and TRPV5 in GBM had greater than 40% Hete Amp levels." (PMID 35174089, 2022). "Gain variations were observed in the great majority of cancers for TRPV6, TRPV5, TRPA1, and TRPC1." (PMID 35831825, 2022).
bone disorder (1 paper, 2023). "Furthermore, several researchers have demonstrated, through gene silencing and other methodologies, that TRPV5 represents a promising therapeutic target for patients exhibiting unfavorable prognoses related to bone disorders." (PMID 37198647, 2023).
infection (1 paper, 2018). The state of being infected such as from the introduction of a foreign agent such as serum, vaccine, antigenic substance or organism. "For lentivirus‐mediated TRPV5 expression, optimal viral particle numbers for infection were based on infection efficiency, determined from the percentage of target cells with green fluorescent protein (GFP)." (PMID 30063124, 2018).
neurological diseases (1 paper, 2025). "Although our findings demonstrated the ability of TRPV5 inhibition to attenuate neuroinflammatory pathways, the involvement of TRPV5 in other pathogenic mechanisms underlying neurological disorders currently remains unclear." (PMID 40708193, 2025).
renal disease (1 paper, 2024). "α-klotho acting as a scaffold for FGF23 binding to the FGFR1-3 receptors has actions independent from FGF23 that include cleavage of NaPi-IIa transporters, regulation of transient receptor potential cation channel subfamily V member 5 (TRPV5) calcium channels and modulation of renal disease." (PMID 37660247, 2024).
TRPV5 also shares sentences with these, for which no sentence is quoted: Osteopenia (2 papers); adenocarcinoma (1); anemia (1); colitis (1); hyperglycaemia (1); Hypokalemia (1); hypophosphatemia (1); idiopathic hypercalciuria (1); Insulin resistance (1); kidney failure (1); medullary cystic kidney disease (1); neurodevelopmental disorder (1); Pseudoxanthoma elasticum (1); renal fibrosis (1); Renal tubular dysfunctions (1); T-cell leukemia (1); ulcerative colitis (1); urinary stones (1).